JAZF1 (JAZF zinc finger 1)
Diseases named in the same sentence as JAZF1 in open-access papers (continued):
Sharing a sentence is not in itself a finding about the gene and the disease.
prostate carcinoma (19 papers, 2009 to 2025). A carcinoma that arises from epithelial cells of the prostate gland. "Recent reports showed that the Jazf1 gene is associated with prostate cancer risk, so we compared Jazf1 expression between human normal prostate and prostate cancer tissues." (PMID 29416651, 2018). "Among the fifteen variants, only one (rs10486567 in JAZF1) shared association with prostate cancer in 5,747 African (OR=0.855, 95% c.i.=0.787–0.929) and in 19,461 Caucasian (OR=0.847, 95% c.i.=0.808–0.889)." (PMID 26967244, 2016). "Of note, while the prostate cancer risk HNF-1 beta variant decreases the risk of T2D, variants of JAZF1 gene are associated with both increased risk for T2D and for prostate cancer." (PMID 19558691, 2009). "Together, Jazf1 was higher expression in human prostate cancer tissues, suggesting Jazf1 may be linked to prostate cancer development." (PMID 29416651, 2018). "Other T2D genes, such as HNF-1 beta and JAZF1, have already been associated with prostate cancer." (PMID 19558691, 2009). "HNF1-beta and JAZF1 genes are associated with T2D and prostate cancer." (PMID 19558691, 2009). "T2D genes, such as HNF-1 beta and JAZF1, have been associated with prostate cancer." (PMID 19558691, 2009). "Hence, we investigated whether the expression of Jazf1 is associated with prostate cancer progression." (PMID 29416651, 2018). "From the Fisher gene set, JAZF1 (JAZF zinc finger 1) has been shown to promote prostate cancer progression through JNK/Slug, leading to enhanced EMT." (PMID 32252623, 2020). "Based on these data, we performed additional experiments to identify the molecular mechanism through which Jazf1 acts in prostate cancer cell lines." (PMID 29416651, 2018). "We found that Jazf1 accelerates prostate cancer progression in vivo and that prostate cancer cells change phenotypes, proliferation, and colony formation upon Jazf1 expression." (PMID 29416651, 2018). "Prostate cancer tissue samples exhibited higher expression of Jazf1 than a normal prostate tissue from the same patient." (PMID 29416651, 2018). "Both vimentin and Slug were significantly increased in Jazf1-overexpressing prostate cancer cell lines." (PMID 29416651, 2018). "In this study, we demonstrated that Jazf1 contributes to prostate cancer progression through up-regulating JNK/Slug." (PMID 29416651, 2018). "Especially, the downstream signaling of Jazf1 that promotes prostate cancer was determined in vitro." (PMID 29416651, 2018). "The levels of Jazf1 mRNA and protein were increased in human prostate cancer tissues compared to adjacent normal prostate tissues." (PMID 29416651, 2018). "We found that Jazf1 promoted prostate cancer cell proliferation and invasion by increasing the subsequent expression of JNK and Slug." (PMID 29416651, 2018). "To investigate the effects of Jazf1 in prostate cancer, we established prostate cancer cell lines stably overexpressing Jazf1." (PMID 29416651, 2018). "In conclusion, our results showed that Jazf1 promotes prostate cancer progression via up-regulating JNK/Slug expression both in vitro and in vivo." (PMID 29416651, 2018). "On this basis, we generated Jazf1-overexpressing human prostate cancer cell lines, DU145 (androgen-independent) and LNCaP (androgen-dependent)." (PMID 29416651, 2018). "Taken together, these results suggest that Jazf1 plays an important role in both androgen dependent and independent prostate cancer." (PMID 29416651, 2018). "The Jazf1 pathway, which is both androgen dependent and independent, can also be a therapeutic target of both primary prostate cancer and CRPC." (PMID 29416651, 2018). "For instance, lead exposure was found to mediate the association between JAZF1 gene rs10486567 and prostate cancer in African–American men but not in white men." (PMID 38873569, 2024). "Additionally, JAZF1 functions in malignancies, especially endometrial stromal tumours and prostate cancer." (PMID 31357957, 2019).
prostate carcinoma (continued). "In addition, using Jazf1 overexpressing prostate cancer cell lines, DU145 and LNCaP, we found Jazf1 promoted cell proliferation and colony formation ability." (PMID 29416651, 2018). "Both Slug and Jazf1 promote prostate cancer tumorigenesis, but the relationship between them is still unknown." (PMID 29416651, 2018). "Additionally, we observed that Jazf1 is expressed higher in human prostate cancer tissues than in normal tissue." (PMID 29416651, 2018). "A variety of evidence indicates a correlation between Jazf1 and prostate cancer." (PMID 29416651, 2018). "The expression of Jazf1 in prostate cancer tissues was higher than in normal tissues." (PMID 29416651, 2018). "To assess downstream signaling of Jazf1, we performed a microarray in prostate cancer cell lines." (PMID 29416651, 2018). "Therefore, Jazf1 may be a crucial factor for prostate cancer progression, suggesting that Jazf1 is a promising new therapeutic target for prostate cancer and CRPC." (PMID 29416651, 2018). "However, the role of Jazf1 in prostate cancer is still poorly understood." (PMID 29416651, 2018). "Taken together, Jazf1 increases the phosphorylation of JNK/AP-1, enhancing Slug expression to promote prostate cancer proliferation." (PMID 29416651, 2018). "Although Jazf1 is known to be involved in prostate cancer, the mechanism of interaction between Jazf1 and prostate cancer has not yet been elucidated." (PMID 29416651, 2018).
Obesity (15 papers, 2008 to 2025). Accumulation of substantial excess body fat. "As obesity-associated chronic inflammation contributes to insulin resistance, JAZF1 has been identified as a potential target for therapeutic strategies for T2D due to its role in mitigating insulin resistance." (PMID 40283858, 2025). "Previous studies have found variants within JAZF1 to be associated separately with T2D, obesity phenotypes, as well as, height." (PMID 37377600, 2023). "In the current study, we demonstrated that JAZF1 expression was markedly down-regulated in obesity-associated mice and nonalcoholic fatty liver disease (NAFLD) patients." (PMID 30154417, 2018). "This study provides new insights into the JAZF1 function in adipose development and metabolism, informing strategies for treating obesity and related metabolic disorders." (PMID 34407873, 2021). "A previous study showed that JAZF1 transgenic mice have a natural resistance to HFD-induced obesity." (PMID 29765984, 2018). "Thus, JAZF1 might influence metabolic regulation, adipose development, adipocyte differentiation, obesity, and insulin resistance through indirectly NR2C2-mediated transcriptional regulation." (PMID 34407873, 2021). "Two studies agreed that genes JAZF1 and NAV1 had CpG sites significantly affected by PA relating to obesity." (PMID 40283858, 2025). "JAZF1 overexpression in transgenic mice improved insulin sensitivity and protected HFD-induced obesity." (PMID 34407873, 2021). "In the current study, we employed HFD diet with a prolonged feeding for one year to establish a model of obesity with hepatic steatosis in WT and JAZF1-Tg mice, which mimics human NAFLD to explore the role of JAZF1 in age and HFD-related NAFLD in vivo." (PMID 30154417, 2018). "In summary, the present study for the first time provides evidence that hepatic JAZF1 (gene/protein) expression is decreased in patients and mice with NAFLD, while JAZF1-Tg mice are protected against age-related and HFD-induced obesity and hepatic steatosis." (PMID 30154417, 2018).
Insulin resistance (14 papers, 2009 to 2025). Increased resistance towards insulin, that is, diminished effectiveness of insulin in reducing blood glucose levels. "Compared to the control mice, the JAZF1-deficient mice had less adipose tissue mass and showed insulin resistance, with a perturbed lipid profile." (PMID 34407873, 2021). "The most critical feature caused by the JAZF1 deficiency was reducing adipose development, which led to insulin resistance." (PMID 34407873, 2021). "Insulin resistance is associated with immune system dysfunction and chronic low-grade inflammation, but the exact role of JAZF1 in T2DM is still poorly understood." (PMID 29765984, 2018). "However, although JAZF1-deficient mice showed adiposity reduction, their insulin resistance was more developed than control mice." (PMID 34407873, 2021). "Our current finding suggests that TCF7L2, together with JAZF1 variants, may indirectly impart insulin resistance through joint modulation of lipid metabolism." (PMID 20018066, 2009). "The collaborative action of JAZF1 and PPAR-γ was implicated in promoting Treg differentiation and regulating insulin resistance by modulating pro- and anti-inflammatory cytokine expression." (PMID 41227365, 2025). "Accordingly, Jazf1 KO mice develop insulin resistance that is further exacerbated by high-fat diet feeding." (PMID 37091973, 2023). "Mice with increased JAZF1 expression showed marked improvement in insulin resistance and metabolic profile with reduced fasting plasma insulin and glucose levels." (PMID 34440550, 2021). "It has been shown that mice with increased expression of JAZF1 exhibited decreased insulin resistance and reduced inflammation in fat tissue with decreased release of pro-inflammatory cytokines." (PMID 34440550, 2021). "JAZF1 is a transcriptional cofactor involved in gluconeogenesis, lipid metabolism, and insulin resistance; it is related to JAZF1 expression in type 2 DM." (PMID 33921168, 2021). "Jazf1 is a zinc finger protein and an inhibitor of the Nuclear receptor subfamily 2, group C, member 2 (Nr2c2), which is involved in insulin resistance, glucose and lipid metabolism, and regulation of peroxisome proliferator-activated receptor (PPAR)α, β/δ, γ." (PMID 32244869, 2020). "Disruption of JAZF1 in iPSCs derived from knockout mice leads to reduced size and impaired differentiation of insulin-producing β-cells, resulting in decreased insulin production and insulin resistance." (PMID 41227365, 2025). "Consequently, JAZF1 overexpressing animals are protected against diet-induced insulin resistance and related metabolic dysfunctions." (PMID 37091973, 2023). "With increase in EAT thickness, the levels of CRP, IL-6, visfatin, and JAZF1 also increase, which can induce hyperglycemia, insulin resistance, and vascular endothelial dysfunction, etc., promoting the occurrence and development of atherosclerosis, leading to macroangiopathy." (PMID 33722242, 2021). "Moreover, JAZF1 decreases insulin resistance by increasing the expression of glucose transporters GLUT in the liver, adipose tissue, skeletal, muscle, and cardiomyocytes." (PMID 34440550, 2021). "Therefore, this study aimed to determine how JAZF1 affects chronic low-grade inflammation, ATMs, and antigen presentation in a mouse model of diet-induced insulin resistance." (PMID 29765984, 2018). "Therefore, JAZF‐1 could be explored as a novel therapeutic agent to prevent the progression of insulin resistance." (PMID 36734198, 2023). "Therefore, the JAZF1 heterozygous deletion caused insulin resistance but did not affect energy metabolism." (PMID 34407873, 2021). "JAZF1 and PPAR-γ were examined for their roles in Treg differentiation, inflammation, and insulin resistance using a transgenic mouse model." (PMID 41227365, 2025). "Here, we investigated the roles of JAZF‐1 and PPAR‐γ in VAT Treg differentiation, inflammation and insulin resistance using a transgenic mouse model." (PMID 36734198, 2023).
Insulin resistance (continued). "In this study, we investigated the mechanism of action of JAZF‐1 and PPAR‐γ in VAT Tregs differentiation and inflammation during the progression of insulin resistance using a mouse model." (PMID 36734198, 2023). "High‐fat diet induced insulin resistance in male C57BL/6 wild‐type mice and was used to examine the effect of JAZF‐1 and PPAR‐γ on VAT Tregs." (PMID 36734198, 2023). "Altogether, we believe that JAZF‐1 and PPAR‐γ function synergistically to reduce insulin resistance in VATs." (PMID 36734198, 2023). "In the current study, we focused on SNPs of three genes (JAZF1, IGF1, and IGF2BP2) which have been shown to affect lipid metabolism and insulin resistance." (PMID 33390804, 2021). "Five SNPs in three genes (rs864745 in JAZF1, rs35767 in IGF1, and rs4376068, rs4402960, and rs6769511 in IGF2BP2) contributing to insulin resistance involving lipid metabolism were genotyped." (PMID 33390804, 2021). "Five SNPs in three genes (rs864745 in JAZF1, rs35767 in IGF1, and rs4376068, rs4402960, and rs6769511 in IGF2BP2) that contribute to insulin resistance involving lipid metabolism were genotyped using the MassArray method in a Chinese population." (PMID 33390804, 2021). "Mouse models of high-fat diet- (HFD-) induced insulin resistance were induced using C57BL/6J and JAZF1-overexpressing (JAZF1-OX) mice." (PMID 29765984, 2018). "Therefore, this study aimed to assess the mechanism of action of JAZF‐1 and PPAR‐γ on the progression of insulin resistance in VAT Tregs." (PMID 36734198, 2023). "Furthermore, a potential synergistic effect between JAZF‐1 and PPAR‐γ, which plays a key role in insulin resistance, was observed." (PMID 36734198, 2023). "Whether JAZF‐1 and PPAR‐γ mediate VAT Treg differentiation to promote the inhibition of chronic inflammation and insulin resistance remains unclear." (PMID 36734198, 2023). "We found that JAZF‐1 and PPAR‐γ could promote Tregs differentiation and regulate insulin resistance by synergistically decreasing the expression levels of TNF‐α, IL‐1β and IL‐6 and increasing those of IL‐10 and TGF‐β." (PMID 36734198, 2023).
endometrial stromal tumor (12 papers, 2009 to 2024). Neoplasms of the endometrial stroma that sometimes involve the myometrium. "Chromosomal aberrations involving this gene are associated with the pathogenesis of endometrial stromal tumors, and JAZF1 itself acts as a transcription repressor." (PMID 32766158, 2020). "Its human ortholog, JAZF1, appears to be involved in transcriptional repression and has been associated to endometrial stromal tumors." (PMID 32432549, 2020). "Prominent in our list of DM+DE genes is JAZF1, encoding a nuclear protein and transcriptional regulator that is affected by chromosomal rearrangements in endometrial stromal tumors." (PMID 28125717, 2017). "The protein functions as a transcriptional repressor of an orphan nuclear receptor (NR2C2) and chromosomal aberrations in the JAZF1 region associate with endometrial stromal tumors." (PMID 19789630, 2009). "JAZF1 is a transcriptional repressor associated with a role in endometrial stromal tumors." (PMID 19343178, 2009). "For example, JAZF1, which is regulated by miR-200b/c, is a proto-oncogene known to be affected by chromosomal translocation in endometrial stromal tumors." (PMID 29357938, 2018). "Intriguingly, among the TF genes with DM we also found JAZF1, a proto-oncogene affected by chromosomal translocations in endometrial stromal tumors." (PMID 28125717, 2017). "The JAZF1/JJAZ1 fusion has been identified in areas of smooth muscle differentiation in endometrial stromal neoplasms (50% of the cases)." (PMID 20368795, 2010). "Immunohistochemically, the round-cell component usually shows > 70% cyclin D1 nuclear staining of the tumor cells with homogenous moderate to strong intensity, in contrast to the form of scattered positive cells (< 5%) in classic JAZF1 rearranged endometrial stromal tumors." (PMID 31615558, 2019). "It has been reported that JAZF1 is a component of gene fusion with SUZ12, which is found in endometrial stromal tumor." (PMID 24586834, 2014).
atherosclerosis (6 papers, 2017 to 2025). A disease characterized by the build-up of fatty material and calcium deposition in the arterial wall resulting in partial or complete occlusion of the arterial lumen. "Intriguingly, several previous studies have shown the association of JAZF1 with atherosclerosis development and with the cell cycle of VSMCs." (PMID 34910364, 2022). "For instance, it was found that upregulated JAZF1 could suppress the progression of atherosclerosis in ApoE‐deficient mice via repression of hepatic cholesterol synthesis with the involvement of CREB." (PMID 34910364, 2022). "Therefore, the decreased expression of JAZF1 in prediabetes may be associated with the development of atherosclerosis." (PMID 33921168, 2021). "In this study, we set out to investigate the effect of macrophages‐derived EVs (M‐EVs) containing miR‐19b‐3p in the progression of atherosclerosis, with the involvement of JAZF1." (PMID 34910364, 2022). "Collectively, this study demonstrates that M‐EVs containing miR‐19b‐3p accelerate migration and promotion of VSMCs through targeting JAZF1, which promotes the development of atherosclerosis." (PMID 34910364, 2022). "Moreover, the specific mechanisms regarding the involvement of miR‐19b‐3p and JAZF1 in atherosclerosis warrant further examination." (PMID 34910364, 2022). "In the current study, we explored the role of M‐EVs containing miR‐19b‐3p in atherosclerosis and identified that M‐EVs containing miR‐19b‐3p elicited stimulative functions on atherosclerosis development through inhibition of JAZF1 by facilitating the migration and proliferation of VSMCs." (PMID 34910364, 2022). "It has been reported that upregulated JAZF1 could protect ApoE−/− mice against atherosclerosis through inhibition of hepatic cholesterol synthesis in a CREB‐dependent manner." (PMID 34910364, 2022). "In this study, our dual‐luciferase gene reporter assay confirmed that miR‐19b‐3p could targeted and downregulate JAZF1 in VSMCs during the development of atherosclerosis." (PMID 34910364, 2022). "Overexpression of JAZF1 protected against the development of atherosclerosis in mice." (PMID 27791988, 2017). "For novel atherosclerosis loci, 4 regions overlapped the most frequently across all stages of multi-trait analyses (nearest gene: BNC2, GPATCH2, INSR, JAZF1)." (PMID 40313769, 2025). "Juxtaposed with another zinc finger protein 1 (JAZF1), also known as TAK1-Interacting Protein 27, is closely related to various diseases such as atherosclerosis and T2DM." (PMID 33722242, 2021).
Hyperglycemia (6 papers, 2013 to 2022). An increased concentration of glucose in the blood. "JAZF1 is a metabolic regulator to improve lipid metabolism and resist hyperglycemia through multiple metabolic signaling pathways in T2D." (PMID 35846288, 2022). "Previous studies have shown that JAZF1 regulates carbohydrate metabolism, preventing hyperglycemia through the regulation of the enzymes phosphoenolpyruvate carboxykinase (PEPCK) and glucose-6-phosphatase." (PMID 34440550, 2021). "This may suggest that hyperglycaemia and dyslipidaemia may reduce JAZF1 expression." (PMID 34440550, 2021).